TGM2 (transglutaminase 2)
Diseases named in the same sentence as TGM2 in open-access papers (continued):
Sharing a sentence is not in itself a finding about the gene and the disease.
cancer (continued). "further found that cancer cells could restrict T-cell motility and suppress the intratumoral accumulation of T cells by assembling a transglutaminase-2 (TGM2)-dependent filamentous coating of CXCL12-keratin-19 (KRT19) heterodimers." (PMID 37359565, 2023). "Hence, inhibiting TGM2 represents a realistic approach to reversing these processes in cancer cells." (PMID 37232732, 2023). "Future in vivo tests and clinical trials may facilitate the application of TGM2 inhibitors for the therapy of cancer and other diseases." (PMID 37735413, 2023). "A biological role of TGM2 in cancer cell survival, metastasis and invasion was reported." (PMID 37443286, 2023). "However, the role of TGM2 in cancer is still controversial, with some reports suggesting it is a potential tumor suppressor and others suggesting it is a tumor promoter." (PMID 37115802, 2023). "Furthermore, as the relationship between galectins and cancer has long been investigated, these sugar binders are also likely to have a hand in the epigenetic modulation connected to TGM2-mediated protein serotonylation." (PMID 36831672, 2023). "As we previously reported aberrant expression of a truncated form of TG2 (TGM2_v2) displaying a new epitope in multiple cancer cell lines, we raised an antibody towards the unique epitope (in exon 10b) to evaluate the presence of this TG2 isoform in PC3 and DU145." (PMID 37160910, 2023). "This specific accumulation of the truncated isoform TGH likely depends on the stall/interference of RNApol II during transcription, promoting the use of an alternative polyadenylation site along the TGM2 gene, as already described for other types of cancer cells." (PMID 34975314, 2022). "Tissue transglutaminase 2 (TG2) has been reported as a major player across several types of cancer." (PMID 36471278, 2022). "The additional, higher-molecular-weight CXCL12–KRT19 complexes formed with recombinant proteins may indicate that cancer cells have additional constraints on the TGM2-mediated cross-linking of these proteins." (PMID 35046049, 2022). "The action process of TGM2 is closely connected with the various stages of tumor growth, including the epithelial-mesenchymal transition, apoptosis, differentiation, and aggressive metastatic phenotype formation of cancer stem cells." (PMID 35669563, 2022). "Notably, KRT19 has been recently described to protect cancer cells from the immune system, acting in concert with transglutaminase 2 (TGM2) which was also found to be elevated at the mRNA level in Ptenflox/flox prostates of 20-week-old mice." (PMID 36291720, 2022). "Interestingly, TGM2 has been shown to play a role in mitochondrial function and cancer therapy resistance." (PMID 34584066, 2021). "In addition, n-Myc and c-Myc contribute to the regulation of TG2 expression by recruiting histone deacetylase 1 protein to the TGM2 promoter in cancer cells." (PMID 34360011, 2021). "TGM2 gene expression is regulated by various cellular events, including apoptotic stimuli, viral infection, endoplasmic reticulum (ER) stress, hypoxia/ischemia, inflammation, tissue remodeling, and cancer." (PMID 34360011, 2021). "Furthermore, IL-1β induces IL-6 production by transglutaminase 2- (TG2-) expressing MCF-7 cells through NF-κB-, PI3K-, and JNK-dependent mechanisms, ultimately increasing the stem-cell-like phenotype of cancer cells associated with drug resistance." (PMID 34602858, 2021). "Given that TGM2 expressed in macrophages also plays a modulatory role in tissue inflammation, targeting TGM2 in GC could be an effective strategy for modulating tumor-promoting inflammation by regulating both cancer cells and macrophages." (PMID 32467608, 2020).
cancer (continued). "In addition to cancer cells, macrophages express TGM2, and TGM2 reportedly participates in macrophage phagocytosis of apoptotic cells." (PMID 32467608, 2020). "Moreover, TGM2 has been suggested to be involved in epithelial–mesenchymal transition (EMT) and the cancer stem cell phenotype, which are highly associated with aggressive cancer phenotypes, in breast, ovarian and squamous cell carcinomas." (PMID 32467608, 2020). "However, in cancer tissue samples with strong expression of TGM2 in GC cells, 73.3% (22/30) of the samples showed high expression of the macrophage marker CD163 (Fisher's exact test, P = 0.006)." (PMID 32467608, 2020). "Transglutaminase 2 closed form is considered a pro-survival factor for cancer and CSCs." (PMID 30691081, 2019). "Scattered evidence suggests that TGM2 might be involved in several types of cancers including glioma." (PMID 29434213, 2018). "Transglutaminase 2 (TG2) plays important roles in cell survival and cancer progression." (PMID 28715877, 2017). "The inhibition of anti-autophagic proteins, such as Bcl2, PKCδ, and tissue transglutaminase 2 (TG2), may lead to autophagic cell death in some apoptosis-resistant cancers." (PMID 27658240, 2016). "To determine whether the dual inhibition of mTORC1 and TGM2 could induce cancer cell apoptosis, we analyzed PI and ANNEXIN V staining of tsc2-/- MEF cells by flow cytometry." (PMID 26872016, 2016). "The transamidation activity of TGM2 has been implicated in apoptosis by interacting with BAX or cross-linking CASP3/Caspase 3 and RB1/pRB to inhibit apoptosis in various cancer cell lines." (PMID 26956429, 2016). "The role of TGM2 in cancer is quite complex and remains poorly understood." (PMID 26956429, 2016). "We therefore hypothesized that combined targeting of both mTORC1 and TGM2 would promote cancer cell death." (PMID 26872016, 2016). "Our preliminary data demonstrate that combined rapamycin treatment and TGM2 blockade could be beneficial to mTORC1-hyperactive cancer cell treatment." (PMID 26872016, 2016). "The utilization of bioorthogonal PTM targeting approaches in proteomic studies supports the regulatory roles of TGM2 in cancer development suggesting that targeting the pathways by which TGM2 mediates monoaminylation could serve as a promising anticancer strategy." (PMID 41001731, 2025). "TGM2-high tumors showed significant reductions in Th1 cells (P = 0.0048) and Th2 cells (P = 0.002), with concurrent increases in M2 macrophages (QUANTISEQ/XCELL, P < 0.0001), cancer-associated fibroblasts (P < 0.0001), hematopoietic stem cells (P < 0.0001), and endothelial cells (P < 0.0001)." (PMID 41050683, 2025). "We speculate that since the active secretion of TGM2 is regulated by ATP-activated P2X7R, the reduction in Glu intake after TGM2 silencing, coupled with the cancer cells’ energy demands, leads to sustained activation of P2X7R by exogenous ATP, stimulating mitochondrial GLS energy metabolism signals." (PMID 41469519, 2025). "Moreover, TGM2 plays a constructive role in cancer immunology." (PMID 39115570, 2024). "Tgm2 and Paqr4 may provide suppressive effects in some aggressive cancer cells." (PMID 34202278, 2021). "In addition, TGM2 confers radioresistance in different types of cancer cells." (PMID 34584066, 2021). "Thus, TGM2 may enable the acid‐adapted cancer cells to engineer and change the ECM by even more advanced mechanisms that collagen deposition." (PMID 33294017, 2020). "Transglutaminase 2 has been reported as one of key enzymes that is involved in all stages of carcinogenesis; the molecular mechanisms of action and physiopathological effects depend on its expression or activities, cellular localization, and specific cancer model." (PMID 30691081, 2019). "Moreover, we previously reported that silencing of transglutaminase 2 (TGM2) inhibited cancer cell proliferation and invasion and that TGM2 may function as an oncogene in ccRCC." (PMID 29796168, 2018).
cancer (continued). "One of the major similarities between mf- and cancer cell line- exposed monocytes is the significant upregulation in the mRNA levels of IL-1β (associated with inflammation or M1 phenotype), MMP9 (associated with angiogenesis), and TGM2 (associated with M2 phenotype)." (PMID 29668679, 2018). "In HCC, CAF-derived IL-6 triggers EMT in cancer cells via activation of the IL-6/JAK/STAT3 axis, which induces transglutaminase 2 (TG2) expression and promotes the mesenchymal phenotype." (PMID 40918452, 2025). "Transglutaminase 2 (TGM2) plays a crucial role in the epithelial–mesenchymal transition and TRAIL resistance; its increased level contributes invasion and migration in cancer cells." (PMID 38893149, 2024). "In A431 tumor cells, TGM2 activates PI3K/Akt signaling pathway that results in the upregulation of MMP-9 and an increase in cell adhesion, migration, invasion, and cancer metastasis." (PMID 36831225, 2023). "The mRNA expression level of FXYD3, LGALS4, USH1C, ECI2, TGM2, and HMGA2 genes which are involved in EMT, drug resistance, and cancer progression were measured in HCT116/OX-R4.3 and HCT116/OX-R10 cells by qRT-PCR." (PMID 37535601, 2023). "Of these genes, FSCN1 was upregulated across all cancer types as compared to normal tissues, whereas ITGA5 and TGM2 were only upregulated in 70% of the tumors." (PMID 36978029, 2023). "The metastases formed with PDA cells expressing both KRT19 and TGM2 exhibited the CXCL12–KRT19 coating, and cancer cell nests excluded T cells." (PMID 35046049, 2022). "The cancer-related GSTM1, YAP1 and TGM2 genes showed most significant correlation with expression among the FA-HNSCC amplified genes." (PMID 34997070, 2022). "These experiments predicted that preventing expression by cancer cells of either KRT19 or TGM2 would impair formation of the CXCL12–KRT19 coating and allow T cells to accumulate within cancer cell nests." (PMID 35046049, 2022). "Also, the expression of genes in this network could be highly influenced by the slight changes in gene expression levels of TGM2, producing relevant biological effects such as interleukin stimulation, cancer dissemination and metastases, and chemotherapeutic agent-resistance." (PMID 34449674, 2021). "TGM2 is overexpressed in tumor cells in patients with CRC and transamidation activity is increased in cancer tissue." (PMID 34103685, 2021). "Transglutaminase-2 (TG2) is an enzyme primarily involved in protein cross-linking, which has been shown to play a role in the development and progression of numerous cancers." (PMID 34205140, 2021). "Remarkably, TGM2 expression was also negatively correlated to both OS and PFS in the radiotherapy treated cancer patients, as well as the overall survival of all patients." (PMID 34225780, 2021). "To validate the overexpression of TGM2 in our acid‐adapted cells, we performed Western blots and immunocytochemistry (ICC) on AA and NA MCF‐7 cancer cells." (PMID 33294017, 2020). "Expression of several genes known to be involved in cancer progression were identified by this method, including HMGA2, FHL1, SLC2A3, ADAMTS1, UPP1, and TGM2." (PMID 32054828, 2020). "By binding to extracellular partners like annexin A2 and transglutaminase-2, S100A4 can also hinder cell-ECM adhesion of cancer cells." (PMID 31652274, 2019). "Transglutaminase 2 (TG2), a multifunctional protein, is reported in regulating the cancer stem cell (CSC) phenotype in various cancers." (PMID 31360304, 2019). "Similar to cancer cell lines, but less dramatically, mf altered the mRNA expression of IL-1β, CCL13, TGM2 and MMP9." (PMID 29668679, 2018).
cancer (continued). "Transglutaminase 2 (EC 2.3.2.13; TG2 or TGase 2) plays important roles in the pathogenesis of many diseases, including cancers, neurodegeneration, and inflammatory disorders." (PMID 30297644, 2018). "Transglutaminase 2 (TG2), a GTP binding regulatory protein, is an important cancer stem cell survival and therapy resistance factor." (PMID 30349644, 2018). "TGM2 can activate NF-κB and focal adhesion kinase (FAK) tyrosine kinase, in turn activate anti-apoptotic pathways to allow cancer cells to become immortalized." (PMID 25247996, 2014). "As transglutaminase 2 (TG2), which has been associated with inflammatory signaling, has been suggested to play a role in tumor behavior, we propose that TG2 may be an important linker inducing interleukin (IL)-6-mediated cancer-cell aggressiveness, including distant hematogenous metastasis." (PMID 21967801, 2011). "Transglutaminase 2 (TG2), a pro-inflammatory protein, has received considerable attention recently for its potential role in cancer cells." (PMID 20967228, 2010). "Transglutaminase 2 (TG2) is a multifunctional protein and plays a role in cancer progression." (PMID 40564959, 2025). "Other TGs, such as TGM2, modulate IL6 expression in various cancers, promoting tumor progression." (PMID 41425727, 2025). "In particular, TGM2 alternative splicing emerges as one of the mechanisms that increase cell-type-dependent TG2 functional complexity, and whose dysregulation seems to play a role in several pathologies including cancer and neurodegeneration." (PMID 38667282, 2024). "In addition, the increased expression of TGM2 in different cancer cells can induce epithelial-mesenchymal transformation (EMT) and promote the invasion and drug resistance of cancer cells." (PMID 37115802, 2023). "Third, when a preformed, noncovalent complex of KRT19 and CXCL12 was incubated with TGM2 at 20 °C, a covalent CXCL12–KRT19 heterodimer was generated that resembled that which is associated with cancer cells." (PMID 35046049, 2022). "Transglutaminase 2 (TG2) is a multifunction enzyme involved in inflammation and cancer." (PMID 35201498, 2021). "Although TGM2 is not a TF, it can trigger cancer progression by regulating master TFs or promoting TF nuclear translocation." (PMID 33738254, 2021). "Furthermore, a recent study showed that PDAC excludes T cells and resists inhibitors of PD-1 checkpoints when cancer cells are coated with covalent heterodimers of CXCL12 and keratin 19 (KRT19) formed by transglutaminase-2 (TGM2)." (PMID 35008248, 2021). "In cancer tissue samples with negative/weak or moderate expression of TGM2 in GC cells, 20.0% (1/5) and 37.5% (9/24) of the samples, respectively, showed high expression of the macrophage marker CD163." (PMID 32467608, 2020). "In particular, TGM2 is regulated by canonical and non-canonical nuclear factor (NF)-κB pathway, that represents a key player in inflammation, cancer development, and progression." (PMID 30691081, 2019). "Although there were major differences between cancer cell line exposed- and mf-exposed monocytes, mRNA expression of IL-1β, MMP9, and TGM2 was shown to be significantly upregulated in monocytes following exposure to either stimuli compared to unexposed monocytes." (PMID 29668679, 2018). "Additional repressed genes were ANGPTL2, TGM2, IL-6, CSF1R, TNFSF12 as well as a key regulatory MAP kinase ERK1/2 (MAPK3), all known to stimulate chronic inflammatory signaling in the tumor microenvironment and to promote cancer metastasis." (PMID 24498382, 2014). "Transglutaminase 2 (TGM2) is an enzyme involved in cell proliferation, differentiation and apoptosis and could mediate chemoresistance in cancer cells." (PMID 23865481, 2013). "Interestingly, TGM2 mRNA levels showed an opposite trend, presenting a significantly higher expression in SKCM neoplastic samples compared to controls, exhibiting the highest mRNA expression levels upon all the TGs in SKCM cancer samples." (PMID 35725560, 2022).
cancer (continued). "Four proteins identified in the faecal proteome are potential biomarkers of the cancer, including diacylglycerol kinase (DGKB, DGK), mastermind-like transcriptional coactivator 2 (MAML2), structural maintenance of chromosomes 4 (SMC4), IG domain-containing protein and transglutaminase 2 (Tgm2)." (PMID 35202347, 2022). "In contrast, tumors that contained PDA cells lacking expression of TGM2 had diminished appearance of the CXCL12–KRT19 coating in both wild-type and TGM2-KO mice, indicating that TGM2 must be expressed by the cancer cell." (PMID 35046049, 2022). "Although BNIP3 and TGM2 are associated with drug resistance and provide valuable prognostic markers in a variety of cancers, the expression and significance of BNIP3 and TGM2 have not been investigated in patients with laryngeal SCC receiving postoperative radiotherapy." (PMID 22458929, 2012).